NOX4 (NADPH oxidase 4)
Diseases named in the same sentence as NOX4 in open-access papers (continued):
Sharing a sentence is not in itself a finding about the gene and the disease.
glioma (20 papers, 2011 to 2026). A benign or malignant brain and spinal cord tumor that arises from glial cells (astrocytes, oligodendrocytes, ependymal cells). "In conclusion, the eccentric expression and appearance of NFE2L2 and NOX4 are risk factors in glioma." (PMID 36627482, 2023). "Our findings suggested that the ferroptosis-associated genes NFE2L2 and NOX4 are potential risk prognostic biomarkers and are correlated with immune infiltration in glioma." (PMID 36627482, 2023). "All results revealed that NFE2L2 and NOX4 appeared to be risk factors in glioma." (PMID 36627482, 2023). "In conclusion, these results indicate that NFE2L2 and NOX4 could be risk prognosis biomarkers in glioma, and they bound up with immune infiltration and tumor immunity in tumorigenesis." (PMID 36627482, 2023). "Thus, the high expression levels of TGF-β1 and NOX4 are associated with a higher grade of human glioma." (PMID 34257808, 2021). "Therefore, NFE2L2 and NOX4 may function as a risk prognosis biomarker for glioma and play a vital role in immune infiltration and tumor immunity." (PMID 36627482, 2023). "NOX4 generates ROS using NADPH as a substrate, and one study showed that the activation of NOX4 leads to the overproduction of lipid peroxides and induces ferroptosis in glioma cells." (PMID 38693581, 2024). "Pseudolaric acid B triggers ferroptosis in glioma cells via activation of Nox4 and inhibition of xCT." (PMID 39193375, 2024). "Our analysis proved that low NFE2L2 and NOX4 expression in glioma patients from the TCGA database were significantly related to better pathologic stage and histological grade." (PMID 36627482, 2023). "The cumulative survival of glioma patients with low NFE2L2 or NOX4 expression was significantly longer than that of glioma patients with high expression." (PMID 36627482, 2023). "This means that the expression levels of NFE2L2 and NOX4 would increase with the glioma development." (PMID 36627482, 2023). "Survival curve and prognostic analysis showed that the overexpression of NFE2L2 and NOX4, respectively, has a remarkable link with a worse prognosis in glioma." (PMID 36627482, 2023). "There were 5 ferroptosis-associated genes (KEAP1, NFE2L2, NOX4, ATF4, ASCL4) that have been tested in human glioma with different research methods." (PMID 36627482, 2023). "And the results also showed that the HR value of the survival curve gradually increased with time lapse, which means that the mortality of glioma patients with high NOX4 expression gradually increased with the prolongation of time." (PMID 36627482, 2023). "More importantly, we observed that NFE2L2 and NOX4 expression have a prognostic value in glioma with AUCs of 0.929 and 0.813, respectively." (PMID 36627482, 2023). "This indicates that the NFE2L2 and NOX4 expression-based signatures can better predict the prognosis of glioma." (PMID 36627482, 2023). "The results indicated that NOX4 is mainly distributed in endothelial cells and can affect angiogenesis in glioma." (PMID 36278207, 2022). "To further determine the mechanism of NOX4 involvement in glioma, we compared ROS levels between the control and LX351322 treatment groups." (PMID 36278207, 2022). "A previous study revealed that circulating hypoxic conditions increase ROS production, activate HIF-1, and promote the growth of glioma cells by upregulating the expression of NOX4 mRNA and protein expression in GBM cells." (PMID 35935861, 2022). "Then, we used Western blotting to analyze brucine-induced changes in the protein level of NOX4, which is reported to be overexpressed in gliomas." (PMID 34112960, 2021). "Since NOX4 is thought to be a source of intracellular ROS in several types of cancer and FOXM1 is aberrantly expressed in glioma, we next sought to determine the relationship between NOX4 and FOXM1." (PMID 34740322, 2021). "There was a correlation between TGF-β1 and NOX4 expression in glioma patients in TCGA databases as well as in our tissue specimens." (PMID 34257808, 2021).
glioma (continued). "The expression of FOXM1 and NADPH oxidase 4 (NOX4) in normal brain tissues and glioma was detected in data from the TCGA database and in our specimens." (PMID 34740322, 2021). "In this study, we found that brucine not only induced NOX4 activation but also upregulated the protein levels of NOX4 and SOD1 in glioma cells, knockdown of NOX4 with siRNA obviously prevented brucine-induced increases of superoxide and H2O2." (PMID 34112960, 2021). "As a member of NADPH oxidase, NOX4 is overexpressed in human gliomas and contributed to pseudolaric acid B-triggered glioma cell ferroptosis via increasing H2O2." (PMID 34112960, 2021). "The expression of FOXM1 and NOX4 was increased in glioma specimens compared with normal brain tissues and correlated with poor clinical outcomes." (PMID 34740322, 2021). "As suggested by the TCGA database analysis, NOX4 was highly expressed in glioma, and the upregulation of NOX4 indicated a shorter survival." (PMID 34740322, 2021). "It was previously reported that NOX4 is prominently expressed in various neuroepithelial tumors, and enhanced expression of NOX4 appears to be involved in cell proliferation and survival in glioma cells." (PMID 27043542, 2016). "We also examined the role of Nox4 in cycling hypoxia-induced ROS production because it has been suggested that Nox4 is expressed in human glioma." (PMID 21935366, 2011). "Sixty glioma-associated targets were associated with CHR, such as MDR transporters (ABCB1, ABCC1, ABCG2), cyclin-dependent kinases (CDK1, CDK6), matrix metalloproteinases (MMP2, MMP9, MMP12), and genes related to inflammation or oxidative stress (NOS2, NOX4)." (PMID 40963691, 2025). "In addition, the high expression of NFE2L2 or NOX4 was in an immunosuppressive state, and it correlated with tumor immunity in glioma." (PMID 36627482, 2023). "In this study, NOX4 expression was analyzed in glioma samples from patients and mouse models." (PMID 36278207, 2022). "In our study, ROS production in glioma was strongly regulated by Nox4." (PMID 36278207, 2022). "NOX4-induced ROS production and increased Nox4 expression play key roles in glioma." (PMID 36278207, 2022). "Furthermore, we investigated the effect of NOX4 on angiogenesis in glioma and progression in an in vivo tumor model using the NOX4 inhibitor GLX351322." (PMID 36278207, 2022). "Pseudolaric acid B could trigger ferroptosis by activating NOX4 in glioma, and the knockdown of NOX4 made it resistant to Pseudolaric acid B-induced cell death." (PMID 36230613, 2022). "This indicated that brucine improved H2O2 in glioma cells in vivo via regulation of NOX4 and xCT." (PMID 34112960, 2021). "Our results showed that NOX4 was highly expressed in glioma tissues." (PMID 34740322, 2021). "Furthermore, TGF-β1 and NOX4 expression levels were also related to the prognosis of glioma patients in TCGA database." (PMID 34257808, 2021). "Next, we performed qPCR, IHC, and Western blotting to detect NOX4 expression in glioma tissues." (PMID 34740322, 2021). "NOX4 was time-dependently upregulated by brucine in glioma cells." (PMID 34112960, 2021). "Considering that FOXM1 expression is positively correlated with NOX4 expression in glioma, it is speculated that NOX4 may be involved in the regulation of FOXM1 expression." (PMID 34740322, 2021). "In summary, these results strongly suggest that TGF-β1 and NOX4 might serve as prognostic biomarkers in glioma." (PMID 34257808, 2021). "Furthermore, NOX4-generated ROS are required for the cycling hypoxia-induced glioma invasion and infiltration through the activation of ERK- and NF-κB-mediated MMP-9 expression." (PMID 27043542, 2016). "Specific knockdown of Nox4 expression by RNA interference resulted in cell-growth inhibition and enhanced induction of apoptosis by chemotherapeutic agents, indicating that enhanced expression of Nox4 appears to be involved in cell proliferation and chemotherapy resistance in glioma cells." (PMID 24868315, 2014).
glioma (continued). "Besides, the expression of NFE2L2 and NOX4 was positively correlated with the WHO grade of glioma." (PMID 36627482, 2023). "The natural compound curcumin combined with thioridazine mediates caspase-dependent apoptotic cell death by producing NOX4-induced ROS and by downregulating c-FLIP and MCL-1 in various cancers, including breast, head and neck, and glioma." (PMID 39765861, 2024). "Correlating this expression with survival expectancy in glioma and GBM, a worse prognosis was recorded in the patients with higher levels of NOX4 compared with patients with low NOX4 expression." (PMID 35203105, 2022). "NOX4 downregulation was conducted with the NOX4 inhibitor GLX351322, and ROS production and angiogenesis were detected in glioma tissues." (PMID 36278207, 2022). "Relationship analysis indicated that NOX4 and FOXM1 expression are correlated with each other in glioma." (PMID 34740322, 2021). "Furthermore, we analyzed the correlation of 1, 3, and 5-year cumulative survival rates of glioma patients with NFE2L2 and NOX4 expression." (PMID 36627482, 2023). "The data suggests that NOX4-mediated ROS generation may be a potential target towards the control of MMP expression and glioma invasion." (PMID 27043542, 2016). "Our preliminary data showed that among the five types of NADPH oxidase (NOX1-5), only NOX4 was induced by PMA in U87MG glioma cells (data not shown)." (PMID 27043542, 2016).
Myocardial fibrosis (19 papers, 2015 to 2025). "In cardiac-specific human NOX4 transgenic mice (hNOX4), a significant overexpression of NOX4 was observed with a high level of ROS production and associated myocardial fibrosis under basal condition when compared to littermate controls negative for hNOX4." (PMID 33953837, 2021). "Increased NOX4 expression in male Wistar rats treated with dexamethasone caused sympathetic excitation of the heart and blood vessels, upregulated oxidative stress levels, elevated blood pressure, and caused myocardial fibrosis." (PMID 36407440, 2022). "The inhibition of chymase restores Ang II levels in the myocardium of STZ-induced diabetic hamsters, reversing NOX4-driven OS and myocardial fibrosis." (PMID 40427563, 2025). "Our previous study demonstrated that PRR RNA interference silencing attenuated the inflammatory response, cardiomyocyte apoptosis and myocardial fibrosis in (DCM), which can be associated with lower NOX4 expression." (PMID 36824459, 2023). "TAC‐mediated myocardial fibrosis is enhanced in mice by transgenic overexpression of Nox4, and cardiomyocyte‐specific KO is protective against myocardial fibrosis and left ventricular dysfunction." (PMID 32955172, 2020). "This suggests that NOX4 plays a role in Ang II-induced myocardial fibrosis in DCM, and targeting Ang II or NOX4 could serve as a promising therapeutic approach for DCM." (PMID 40427563, 2025). "Moreover, endothelial-specific NOX4 overexpression in mice protects against myocardial fibrosis, inflammatory cell infiltration and endothelial activation induced by angiotensin II insult." (PMID 41009041, 2025). "AT1 stimulation produces cardiac ROS generation through a number of pathways, including nicotinamide adenine dinucleotide phosphate oxidase 4 (NOX4) and xanthine oxidase (XO), and may be involved in myocardial fibrosis and cardiac remodeling." (PMID 37968296, 2023). "Moreover, ROS can promote myocardial fibrosis via a NOX4-mediated, ROS-ERK1/2-MAP Kinase-dependent mechanism." (PMID 27536244, 2016). "The expressional changes of these common target mRNAs could result in different diseases sharing common general pathomechanisms (e.g., NOX4 regulating oxidative stress in heart and kidney diseases, Col1a2 in myocardial fibrosis and tumor metastasis, BIM in different cancer types, etc.)." (PMID 29765562, 2018). "Alleviated myocardial fibrosis and left-ventricular systolic dysfunction, inhibited NOX2 and NOX4." (PMID 36142538, 2022). "Here, we show that mice overexpressing Nox4 in ECs develop significantly less AngII‐induced myocardial fibrosis without affecting AngII‐induced cardiomyocyte hypertrophy." (PMID 33511759, 2021). "Metabolic characteristics, cardiac function and morphology, myocardial remodeling, myocardial fibrosis (collagen III, α-SMA, and TGF-β), oxidative stress (NRF2, HO-1, SOD, and NOX4), and apoptosis (BAX, Bak, Bcl-2, and Bcl-XL) were analyzed 24 weeks after the different treatments." (PMID 34520392, 2021). "In Sprague-Dawley rats with left anterior descending (LAD) coronary artery ligation, NOX4 adenoviral overexpression abrogated the beneficial effects of endostatin and Tanshinone IIA on myocardial ischemia (MI), and exacerbated LV systolic dysfunction and myocardial fibrosis." (PMID 41009041, 2025).
type 2 diabetes (19 papers, 2012 to 2025). "Catalpol improved hepatic insulin resistance in type 2 diabetes through action on the AMPK/NOX4/PI3K/AKT pathway." (PMID 38029230, 2023). "Mitochondrial ROS is one of the major source of development of type 2 diabetes and long term treatment of palmitate in pancreatic beta cells, NOX-4 derived ROS generation was strongly increased." (PMID 34073736, 2021). "The starting point for thedevelopment of NOX4-selective ligands was the screening of a libraryof 40,000 compounds in T-Rex-293 cells with inducible overexpressionof NOX4 in order to investigate the role of this enzyme in type 2diabetes." (PMID 37650225, 2023). "Based on these findings, the authors proposed that Nox4 mediates pro-apoptotic effects in intact islets under stressful conditions and that selective Nox4-inhibition may be a therapeutic strategy in type 2 diabetes." (PMID 33255484, 2020). "We propose that Nox4 mediates pro-apoptotic effects in intact islets under stressful conditions and that selective Nox4-inhibition may be a therapeutic strategy in type 2 diabetes." (PMID 30265686, 2018). "Interestingly, this study found that aliskiren significantly attenuated only a specific NADPH oxidase subunit p22phoxbutitdid not affect other subunits p47phox and p67phox and isoforms of Nox2 and Nox4 in a type 2 diabetic animal model." (PMID 28753620, 2017). "Catalpol has a protective effect on the endothelium in type 2 diabetes mellitus and its mechanism may be associated with the negative regulation of Nox4 and p22phox expression, inhibiting the oxidative stress reaction response." (PMID 38029230, 2023). "Thus, NOX4 inhibition or modulation may be a therapeutic strategy in type 2 diabetes that targets all types of islets." (PMID 34944680, 2021). "We propose that selective Nox4-inhibition may be a therapeutic strategy in type 2 diabetes." (PMID 30265686, 2018). "Of note, EMPA has been previously demonstrated to prevent the upregulation of NOX4, the highest abundant NOX isoform, in a murine model of type 2 diabetes." (PMID 39042348, 2025). "Metformin as another kind of type 2 diabetes drug approved by FDA, our previous study has shown that it alleviates HSCs aging by inhibiting NOX4-mediated oxidative stress, thus improving long-term HSCs injury induced by IR in mice." (PMID 32774687, 2020).
asthma (18 papers, 2013 to 2025). "In this regard, the role and underlying mechanism of NOX4 in the vascular and airway remodeling, fibroblast proliferation, and vascular smooth muscle hyperplasia/hypertrophy during the progression of asthma, and particularly the IPF, have been well documented." (PMID 27656649, 2016). "LTC4 inhibitors, commonly used for asthma, could find broad clinical use in major human pathologies associated with ER stress-activated NOX4." (PMID 26656251, 2015). "Nicotinamide adenine dinucleotide phosphate oxidase 4 (NOX4) downregulation was found to inactivate the TGF-β1-Smad2/3 pathway in mice with asthma." (PMID 39120302, 2024). "Future studies are needed to evaluate the efficacy and safety of NOX4 blocking in the treatment of asthma." (PMID 39120302, 2024). "In pharmacological inhibition and genetic approaches of asthma model, increased smooth muscle contractility in the airway was repudiated in NOX4." (PMID 35796922, 2022). "In this study, we demonstrated that mechanosensitive ion channel TRPV4 integrates growth factor (TGFβ1) and redox (NOX4) signaling during lung fibroblast differentiation and airway remodeling in asthma." (PMID 32555397, 2020). "Our results demonstrated that at basal levels, LF isolated from asthma patients (DHLF) exhibit higher expression of NOX4 and α-SMA compared to fibroblasts from normal (NHLF) subjects, which were significantly increased in response to TGFβ1." (PMID 32555397, 2020). "Here, we demonstrate that NOX4 integrates TGFβ1 and mechanical signaling in fibroblast differentiation and lung remodeling during asthma." (PMID 32555397, 2020). "For example, NOX2 modulates inflammatory responses in asthma, while NOX4 mediates airway smooth muscle hypercontractility." (PMID 30669315, 2019). "This increased NOX4 expression was also present in vitro with NADPH oxidase-dependent increased ROS generation in primary epithelial cells from patients with asthma with neutrophilic inflammation." (PMID 26836936, 2016). "In vitro NOX4 expression was increased in airway smooth muscle cells from subjects with COPD (n = 5) compared to asthma (n = 7) and upregulated following TNF-α stimulation." (PMID 27435477, 2016). "Bronchial epithelial cells from patients with asthma with neutrophilic airway inflammation exhibit heightened NOX4 expression and ROS generation." (PMID 26836936, 2016). "Hydrogen peroxide-induced reactive oxygen species generation by airway smooth muscle cells in COPD (n = 5) was comparable to healthy controls (n = 9) but lower than asthma (n = 5); and was markedly attenuated by NOX4 inhibition." (PMID 27435477, 2016). "NOX4 has been implicated in a variety of respiratory diseases, including acute respiratory distress syndrome, chronic obstructive pulmonary disease (COPD), lung cancer, and asthma." (PMID 35711428, 2022). "In conclusion, our results suggest that targeting TRPV4/NOX4 signaling may provide a new therapy for lung remodeling in asthma in situations where treatments focused solely on steroids or other conventional treatments have proven ineffective." (PMID 32555397, 2020). "Importantly, we found that NOX4 expression is highly upregulated in experimentally induced asthma model (D. farinae-challenged mice) compared to controls, suggesting an essential role for NOX4 in airway remodeling." (PMID 32555397, 2020). "The TGF-β-induced activation of the reactive oxygen species (ROS)-generating enzyme, NADPH oxidase 4 (Nox4) that induces myofibroblast differentiation, is implicated in ASM proliferation and hypercontractility in asthma, as well as in epithelial ciliary dysfunction in neutrophilic asthma." (PMID 32509793, 2020). "Furthermore, NOX4 expression is increased in airway smooth muscle in asthma, leading to increased ROS production and intrinsic airway smooth muscle hypercontractility." (PMID 32082074, 2019).